IL13RA2 (interleukin 13 receptor subunit alpha 2)
Diseases named in the same sentence as IL13RA2 in open-access papers (continued):
Sharing a sentence is not in itself a finding about the gene and the disease.
colorectal cancer (24 papers, 2013 to 2025). A primary or metastatic malignant neoplasm that affects the colon or rectum. "IL13RA2 has a pro-tumorigenic function in some contexts, notably brain and colorectal cancers, and to a lesser extent pancreatic and ovarian cancers, but the overall relationship between IL13RA2 expression and patient prognosis remains ambiguous." (PMID 40663259, 2025). "IL13RA2 is a cancer testis antigen that has previously been reported in colorectal cancer and gastric cancer (among many other tumor types)." (PMID 41511314, 2025). "In IL-13Rα2-targeted therapy, blocking IL-13Rα2 with monoclonal antibodies inhibited hepatic metastasis of colorectal cancer cells in animals through suppression of the Src-PI3K/AKT pathway." (PMID 39598436, 2024). "IL13RA2 is expressed in nearly 80% of lung cancers, and its expression is also elevated in colorectal cancer sites when compared to that of normal sites." (PMID 37889013, 2023). "Together, these results support the capacity of D1-specific mAbs for blocking IL-13-triggered cell invasion, migration and adhesion in colorectal cancer cell lines positive for IL13Rα2 expression." (PMID 33917458, 2021). "Multiple studies have demonstrated the value of IL13Rα2 as a promising target for different types of metastasis, including colorectal cancer." (PMID 33917458, 2021). "It was reported that IL13Rα2 was overexpressed in metastatic colorectal cancer and inhibition of IL13 binding to IL13Rα2 showed the therapeutic activity in colorectal cancer by reducing metastatic spread." (PMID 33917914, 2021). "In colorectal cancer, treatment with Claramine abolished IL-13-induced cell adhesion to Matrigel at a similar extent to the use of a blocking IL13Rα2 antibody (clone 47), suggesting that both treatments are likely blocking the same pathway." (PMID 32098194, 2020). "We propose that the D-D1 peptide from IL13Rα2 represents a promising therapeutic agent to inhibit metastatic progression in colorectal cancer and, likely, other solid tumours." (PMID 30318506, 2018). "In resection specimens of patients with colorectal carcinoma, IL13RA2 was also expressed in epithelial cells surrounding the tumor, although the intensity of the staining was slightly weaker than in CD and UC patients." (PMID 30619339, 2018). "In addition, in colorectal cancer cells, higher expression of IL-13Rα2 increased invasion activity through activation of Src, and silencing of IL-13Rα2 decreased hepatic metastasis of cancer cells in an in vivo model." (PMID 39598436, 2024). "In addition, overexpression of IL13Rα2 in advanced cancers has paved way for multiple cancers therapies including colorectal cancer." (PMID 35612318, 2022). "Based on these findings, we can think that IL13Rα2-specific mAbs might be used in combination with or alternatively to those mAbs currently used for EGFR targeting in colorectal cancer." (PMID 33917458, 2021). "IL13Rα2 does not present a significant mutation rate in colorectal cancer avoiding extensive testing on natural variants." (PMID 33917458, 2021). "Amperometric detection of IL-13Rα2 by H2O2/hydroquinone (HQ) system revealed a wide dynamic concentration range (2.7–100 ng mL−1), with an LOD value of 0.8 ng mL−1, and can be applied for quick and selective determination of IL-13Rα2 in raw cell lysates from human colorectal cancer cells." (PMID 31878102, 2019). "Elevated levels of IL-13RA2 have been described in several cancers and have been implicated, for example, in metastatization and poor patients’ survival in colorectal cancer and ERα-negative breast cancer." (PMID 30218041, 2018).
colorectal cancer (continued). "Examples include EGFR/IL13Rα2 CAR-T for GBM, CD19/GCC “Coupled CAR” for colorectal cancer (CRC), and TAG - 72/ΔCD47m CAR for ovarian cancer." (PMID 40969260, 2025). "In summary, we have obtained an IL13Rα2-specific antibody 5.5.4 that can inhibit IL-13-mediated FAK, Src and AKT signaling to suppress metastatic liver colonization in colorectal cancer." (PMID 33917458, 2021). "In another study, the same group established a dual electrochemical immunoassay for the simultaneous detection of IL-13Rα2, as well as CDH-17, present in lysates from breast and colorectal cancer cells, respectively, with different metastatic potential." (PMID 31878102, 2019). "In colorectal cancer cells, IL13 signaling through its receptor IL13Rα2 plays a critical role in cell adhesion, invasion and liver metastasis." (PMID 26682245, 2015). "The IL13Rα2 D1 peptide-specific monoclonal antibody 5.5.4 has demonstrated a large capacity for blocking IL13Rα2 signaling capacity and protecting mice against established and non-established liver metastasis in colorectal cancer." (PMID 33917458, 2021). "IL13Rα2 is highly expressed in several human tumors such as colorectal cancer but is absent in normal tissues such as intestinal epithelium." (PMID 27708223, 2016).
ovarian carcinoma (18 papers, 2008 to 2025). A malignant neoplasm originating from the surface ovarian epithelium. "Investigations in pancreatic, colorectal, and ovarian cancer have shown that IL13RA2 overexpression promotes tumor migration and invasion." (PMID 34447744, 2021). "In ovarian cancer (OC), IL-13 was described to regulate cancer invasion and metastasis through IL13Rα2." (PMID 32098194, 2020). "We have also demonstrated that IL-13Rα2 is directly involved in cancer invasion and metastasis in pancreatic and ovarian cancers." (PMID 30572904, 2018). "Our recent studies in animals confirm our observations that IL-13Rα2 is involved in tumor invasion, metastasis and poor survival of animals implanted with human pancreatic and ovarian cancers." (PMID 29168083, 2018). "In addition, it has been shown that IL-13Rα2 promotes tumor invasion and metastasis in mouse models of human pancreatic and ovarian cancers." (PMID 29168083, 2018). "In addition, we have demonstrated that IL-13 can mediate signaling through IL-13Rα2 in human pancreatic and ovarian cancer cells." (PMID 30572904, 2018). "Expression of IL13RA2 is high in ovarian cancer but very low in the normal ovary." (PMID 18560533, 2008). "In addition, IL-13Rα2 is overexpressed in a variety of human tumors such as oral squamous cell carcinoma, breast cancer, clear cell renal cell carcinoma, hepatic cell cancer, ovarian cancer and colorectal cancer." (PMID 27351230, 2016). "Furthermore studies have revealed that IL-13Rα2 mediates metastasis in breast and ovarian cancer." (PMID 27351230, 2016). "IL-13 activated ERK1/2 signaling first followed by AP-1 activation through IL-13Rα2 in ovarian cancer cell lines, which in turn led to induction of MMP in IL-13Rα2 positive tumors." (PMID 30572904, 2018). "We have previously demonstrated that IL-13Rα2 is involved in cancer invasion and metastasis in pancreatic and ovarian cancers in animal models but not affects tumor growth." (PMID 30572904, 2018). "In addition, since IL-13/IL-13Rα2 axis is involved in AP-1 signal transduction pathway in human GBM similar to pancreatic and ovarian cancer, we believe that specific targeting of this pathway may be an important target for therapeutic intervention for GBM therapy." (PMID 30572904, 2018). "We also demonstrated that IL-13/IL-13Rα2 axis is functional in mediating ERK1/2, AP-1 and matrix metalo-proteinase (MMP) activities only in IL-13Rα2-positive cells but not in IL-13Rα2-negative ovarian cancer cells." (PMID 30572904, 2018).
asthma (15 papers, 2005 to 2025). "We compared this treatment effect to fluticasone, a mainstay treatment for asthma, and to soluble (s)IL-13Rα2, a treatment that neutralizes IL-13, a central mediator of type-2 inflammation." (PMID 39592603, 2024). "Pharmacologically active IL-13 inhibitors, such as pitrakinra (an IL-4 mutant), tralokinumab, or the soluble IL-13Rα2, have already been clinically tested for the treatment of other diseases, such as asthma or in tumor therapy." (PMID 37629063, 2023). "Therefore, the role of IL13Rα2/FAM120A in different pathologies open new research lines with important implications in asthma or ulcerative colitis." (PMID 26682245, 2015). "Furthermore, a role for IL13Rα2 has been shown for diverse pathologies, as asthma or ulcerative colitis." (PMID 26682245, 2015). "In addition, soluble IL-13Rα2 is effective in blocking the actions of IL-13, including IgE production, pulmonary eosinophilia and airway hyperresponsiveness in animal models of asthma and humanised IL-13Rα2 is now entering phase I clinical trials in asthma." (PMID 18315837, 2008). "The targets of the FEO‐03 network, IL13, and functional partners IL13RA1, IL13RA2, IL4R, IL6, and TNF were presented in a red box from the asthma diagram of KEGG Pathways." (PMID 40777200, 2025). "The credibility of results has been verified by selecting four genes (IL5RA, CCR3, IL13RA2, TNFRSF8) which were upregulated in Asthma groups, but downregulated in ART + Asthma groups, according to the log2 (fold change) value." (PMID 36998616, 2023). "Functional analysis of disease components yielded all eight GOIs in the respiratory disease category (asthma and/or bronchiolitis and/or viral infections), with two genes (IL4 and IL13RA2) specifically in the COPD/asthma category." (PMID 33526116, 2020). "Secondly, Using RP, we report for the first time an interaction of six genes affecting European ancestry pediatric asthma: rs2243250 (IL4), rs6597 (STUB1) rs11168070 (ADRβ2), rs3024676 (IL4Rα), rs638376 (IL13Rα2) and rs3806446 (CHIA)." (PMID 21387019, 2011). "IL-13 plays a key role in many pathological processes, such as asthma, pulmonary fibrosis, and ulcerative colitis, and IL13 as an inflammatory factor plays an important part in various inflammatory reactions, suggesting IL13RA2 may play an important role in PVR." (PMID 35770008, 2022).
colon cancer (13 papers, 2015 to 2025). "Though our phenotypic data contradict those reported by the Casal group for colon cancer, the pathways identified as differentially active in IL13RA2-deficient cells, namely, AKT, NF-κB, and focal adhesion, overlap." (PMID 40663259, 2025). "Moreover, overexpression of IL13Rα2 in human colon cancer samples was associated to metastasis and poor outcome of patients." (PMID 26682245, 2015). "High levels of IL-13Rα2 were detected by immunoblotting in metastatic colon cancer cell lines, and 66% of tumor samples in patients showed clear overexpression of IL-13Rα2." (PMID 37176567, 2023). "The developed immunosensor was tested for in-situ quantification of IL-13Rα2 expression in both lysed and intact colon cancer cells." (PMID 36144024, 2022). "A colon-cancer-secreted biomarker (IL-13Rα2) has amperometrically been detected, whereas its in situ expression was analyzed either in the intact colon cancer or in the lysed cells." (PMID 36236638, 2022). "Concentrations of IL-13Rα2 from colon cancer cell lysates (SW480, SW620, KM12C, KM12SM) and paraffin-embedded colorectal tissues were in agreement with those reported for the same cells using the MBs-based immunosensor." (PMID 32295170, 2020). "For example, highly metastatic colon cancer cells increase the surface expression of the interleukin-13 receptor Rα2 (IL-13Rα2)." (PMID 32295170, 2020). "By a proteomic approach using colon cancer cells, we identified the proteins that co-immunoprecipitated with IL13Rα2 and found a scaffold protein, FAM120A, also known as C9orf10 or OSSA, as a major interactor." (PMID 26682245, 2015). "In summary, FAM120A is a scaffold protein required for the proper IL13Rα2-triggered signaling, which is involved in colon cancer metastasis." (PMID 26682245, 2015). "In another biosensing report introduced by Alejandro Valverde and collaborators, colon cancer metastasis was electrochemically diagnosed through the development of a novel immunosensor to amperometrically monitor the secreted IL-13Rα2 as the targeting cancer biomarker." (PMID 36144024, 2022). "IL13Rα2 has previously been identified as a target of interest in numerous cancers, including malignant gliomas, pancreatic cancer, melanoma, ovarian cancer, and colon cancer." (PMID 34001278, 2021). "In colon cancer, they determined the scaffolding protein FAM120A to be an essential mediator of IL13/IL13RA2 signaling through FAK, PI3K and Src." (PMID 40663259, 2025). "It has been also reported that IL-13Rα2 signaling requires a scaffold protein, FAM120A, to activate the FAK and PI3K pathways in colon cancer metastasis." (PMID 30165890, 2018). "Consistently, previous studies also reported that IL-13Rα2 mRNA did not be detected by RT-PCR in HT29/B6 colon cancer cells and IL-13/IL-13Rα1 pathway was shown to play a central role in the regulation of intestinal epithelial architecture and function." (PMID 27533463, 2016). "Moreover, the authors showed an inhibition of colonic cancer cell proliferation induced by IL-13 by silencing IL13Ra1, but not IL13Ra2 gene." (PMID 32512917, 2020).
malignant glioma (13 papers, 2007 to 2024). A grade III or grade IV glioma arising from the central nervous system. "A phase I clinical trial (NCT02208362) is currently underway to evaluate the safety and optimal dosing of CAR-T immunotherapy targeting the interleukin-13 alpha 2 receptor (IL13Rα2) for the treatment of patients with relapsed or refractory malignant glioma." (PMID 39531784, 2024). "A possible link has been suggested between c-JUN and c-FOS expression and IL-13Rα2, which is consistent with the expression profile of human IL-13 Rα2 in malignant gliomas." (PMID 36830725, 2023). "Previous studies demonstrated that IL13RA2 was overexpressed in various cancers, such as malignant gliomas, and thyroid Carcinoma." (PMID 35748788, 2022). "An ongoing clinical trial with intraventricular administration of IL-13Rα2 CAR T cells for recurrent or refractory malignant glioma revealed significant tumor volume reduction in one patient, followed by complete response for more than 7.5 months." (PMID 33673696, 2021). "Recombinant adenovirus, which expressed IL-13 on its surface, transferred genes to IL-13Rα2-expressing malignant glioma cells more effectively." (PMID 33450900, 2021). "Interleukin-13 receptor α 2 (IL13Rα2) is a promising tumor-directed antigen of malignant glioma (MG)." (PMID 34819930, 2021). "IL-13Rα2-targeted cancer vaccines also showed effects in malignant gliomas in children, such as peptide-based cancer vaccine." (PMID 33450900, 2021). "H-score for IL13Rα2 in malignant glioma samples according to molecular markers (n = 46)." (PMID 34819930, 2021). "H-score for IL13Rα2 in malignant glioma samples according to clinical characteristics (n = 53)." (PMID 34819930, 2021). "Second-generation IL13Rα2-targeted, 4-1BB co-stimulatory CAR T cells underwent clinical trial whereby CAR T cells were introduced in r/r IL13Rα2+ malignant glioma patients through either intratumoral, intraventricular or dual intratumoral/intraventricular routes." (PMID 36721153, 2023). "Although the exact signalling mechanism of IL-13Rα2 is not yet well-characterised, in malignant glioma, IL-13Rα2 has shown to regulate activation of STAT327 and initiate signalling via activation protein 1 (AP-1)." (PMID 31974500, 2020). "The patient's tumor expressed both EphA2 and IL-13Rα2, and in vitro stimulated PBMC demonstrated superior EphA2883–891 and IL-13Rα2345–353-specific CTL reactivity compared to PBMC samples from two other patients with progressing malignant glioma." (PMID 18093336, 2007).
ependymoma (11 papers, 2020 to 2024). A WHO grade II, slow growing tumor of children and young adults, usually located intraventricularly. "Another study identified three cell surface targets, EPHA2, HER2, and IL13Rα2, that are expressed on medulloblastoma and ependymoma." (PMID 36983330, 2023). "CAR-T EPHA2, HER2 and IL13Rα2 cells, alone or in combination with the CSF are effective against primary, metastatic, and recurrent Group 3 MB in mouse models (as well as ependymomas)." (PMID 37508458, 2023). "Trivalent CAR T cells targeting to HER2, IL13Rα2, and EphA2 demonstrated efficacy in xenograft ependymoma models." (PMID 35265074, 2022). "CAR-T cells with trivalent targets to EPHA2, HER2 and IL13Rα2 did show efficacy in xenograft models of ependymomas." (PMID 32903405, 2020). "EphA2, IL13Rα2, HER2, and Survivin molecules are expressed specifically in ependymomas, and have been shown potentially target for CAR T cell therapy." (PMID 35265074, 2022). "The use of trivalent targets to EphA2, HER2, and IL-13Rα2 of CAR T cells exhibited benefits in preclinical models of recurrent medulloblastoma, GBM, and ependymomas." (PMID 33673696, 2021). "Studies have demonstrated increased expression of EphA2, IL-13Rα2, HER2 and Survivin in ependymomas." (PMID 32903405, 2020). "Moreover, it confirmed that intrathecal delivery of EPHA2, HER2, and IL13Rα2 CAR-T cells is an effective treatment for primary, metastatic, and recurrent group 3 medulloblastoma and PFA ependymoma in a mouse model." (PMID 36983330, 2023). "Similarly, EPHA2, another tyrosine kinase, and IL13Rα2 targets are expressed by MBs (and ependymomas), but not by the developing healthy brain." (PMID 37508458, 2023).